ZEB1 (zinc finger E-box binding homeobox 1)
Diseases named in the same sentence as ZEB1 in open-access papers (continued):
Sharing a sentence is not in itself a finding about the gene and the disease.
cancer (continued). "In line with this, we found ZEB1 to be more highly expressed in basal-like cancers displaying post-EMT gene expression patterns than in basal-like cancers displaying partial-EMT features." (PMID 38111531, 2023). "Gene expression of E-cad is reduced in most cancer cells and regulated by E-cad transcriptional repressors Snail-1/2, zinc finger E-box-binding homeobox 1 (ZEB1)-1/2, and Twist." (PMID 37653930, 2023). "Overediting impairs the ability of miRNA200b to inhibit ZEB1, inducing an alteration of cancer-cell aggressiveness." (PMID 37958449, 2023). "Consistently, the mRNA expression of Slug and Zeb1, 2 transcription factors critical for epithelial-mesenchymal transition of cancer cells, was decreased in HepG2-NTCP cells where TAOK1 was knocked down." (PMID 36930872, 2023). "The ZEB1 expression in downregulated HOTAIR SKOV3 cells is lower than that in the control, and the decreased ZEB1 expression will lead to an increase in E-cadherin expression in cancer cells." (PMID 38070058, 2023). "We tested protein expression for ZEB1 and the mesenchymal cancer cell proteins MMP2, SNAI2, and CD44 due to their upregulation in GBM vs. normal tissue." (PMID 37761927, 2023). "In agreement with our results, all the studies showed that ZEB1‐circRNAs are upregulated in cancer; however, they identified different targets and functional axes (miR‐337‐3p/TGFBR1, mR‐195‐5p/LOXL2, miR‐448/EEF2K, miR‐200a‐3p/CDK6 and miR‐199a‐3p/PIK3CA)." (PMID 37408496, 2023). "This selection was made given to the strong significance of their deregulation and consistency of the changed expression of multiple ZEB1‐circRNAs and based on the functioning of ZEB1 as a transcription factor related to cancer and hematopoiesis." (PMID 37408496, 2023). "ZEB1 mediates some of the downstream effects of RAS in cancer cells like the maintenance of a stem-like phenotype, cell proliferation, and anoikis resistance." (PMID 37870961, 2023). "All these effects were inverted with overexpression of ZEB1, which substantiates the prospective role of ZEB1 in (cancer) cell stemness." (PMID 38139138, 2023). "Zeb1 is mainly described for its enhancing role in epithelial to mesenchymal transition during cancer and embryonic development, but has recently been linked also to Hematopoietic stem cell renewal and asymmetric cell division." (PMID 36862248, 2023). "For example, Omomyc increased the expression of the ZEB1-suppressing miR-200a/miR-200b/miR-429 cluster, which is well-known due to its anti-proliferative activity in cancer cells." (PMID 37239035, 2023). "By stabilizing Zeb1 in cancer cells and delivering exosomes to induce M2 macrophage polarization, LINC00963 promoted the malignancy and metastasis of LUAD." (PMID 36604626, 2023). "Our new approach utilizing MutZEB1 will be helpful in further elucidating the roles of ZEB1 in cancer biology." (PMID 36910659, 2023). "Breaking the miR-200/ZEB1 mutually inhibitory feedback loop in breast cancer cells through CRISPR/Cas9 can reduce cancer cell metastasis." (PMID 37963558, 2023). "MCF7/Zeb1 cells were transduced with this lentiviral vector to select for the population of cancer cells enriched in Oct4/Sox2 stem factors." (PMID 37372954, 2023). "This event is attributed to the enriched Zn-finger motifs in the ZEB1 protein composition, but it has not been fully elucidated how Zn2+-binding influences the pleiotropic role of ZEB1 through cancer progression." (PMID 36910659, 2023). "We further identified multiple cancer-relevant target genes of the Zn2+-activated ZEB1, among which LOXL1 and LOXL2, in particular, function as pioneer factors for invasiveness." (PMID 36910659, 2023). "ZEB1, another key EMT-TF, has been reported to be directly linked with immunosuppressive effects in cancer." (PMID 36823234, 2023).
cancer (continued). "MIR200CHG is the host gene of two intronic miRNAs – miR-200c and miR-141 – members of the miR-200 family, which has been demonstrated to inhibit the EMT pathway in cancer cells by directly repressing the EMT-inducing transcriptional factors ZEB1 and ZEB240." (PMID 38065939, 2023). "In many cancers models, the repression of the endogenous levels of hsa-miR-429 leads to increased levels of ZEB1 and ZEB2 and consequently to reduced E-cadherin synthesis and increased cellular motility." (PMID 37296866, 2023). "To better understand the role of Zeb1 in this process, we decided to analyze the interactomes of Zeb1 isolated from control and cancer-stem cell-like cultures." (PMID 37372954, 2023). "Another agent promoting EMT is ZEB1 deubiquitinated by ubiquitin-specific peptidase 18 (USP18) in esophageal squamous cell carcinoma, while overall SUMOylation is associated with cancer progression." (PMID 37174083, 2023). "It has been reported that ZEB1 has multiple binding partners, which regulate the expression of many genes through cancer progression." (PMID 36910659, 2023). "In sum, these results suggest that ZEB1 has opposing functions on anchorage-independent cancer cell growth, promoting it in KRASG12D cells but inhibiting it in BRAFV600E ones." (PMID 37870961, 2023). "ZEB1 induces an epithelial-to-mesenchymal transition (EMT) and is associated with worse progression in most carcinomas." (PMID 37870961, 2023). "In particular, cancer cells several rows behind the leading edge exhibited upregulated Notch1, Nrf2, and miR-200c while cells at the leading edge expressed ZEB1, Dll4, and Jagged1." (PMID 35480877, 2022). "Among the Ets family of transcription factors, Ets1, a prototypic member of this family, activates the ZEB1 promoter and induces endogenous ZEB1/2 expression in cancer cells." (PMID 36140527, 2022). "High ZEB1 expression is observed in multiple cancer types, including lymphoma, bladder, brain, breast, cervical, colon, endometrial, gastric, head and neck, liver, lung, pancreatic, renal, and uterine cancer." (PMID 35454770, 2022). "Various miRNAs have shown therapeutic potential by acting on GBM cancer cell migration and invasion via the modulation of ZEB1." (PMID 36402997, 2022). "Among these target genes, ZEB1 has been mentioned to regulate the EMT of cancer cells in cervical cancer and esophageal squamous cell carcinoma." (PMID 36793341, 2022). "At the same time, ZEB1 represses the highly mutagenic theta-mediated end joining (TMEJ) pathway to control the stability of ZEB1-positive cancer-cell genome." (PMID 35110528, 2022). "Our EMT+ subtype exhibit elevated markers VIM, SNAI1, and ZEB1, consistent with our pan-cancer analysis and with known molecular features of epithelial-mesenchymal transition." (PMID 35912202, 2022). "It has been indicated that the miR-200 family determines the epithelial phenotype of cancer cells by targeting the E-cadherin repressors ZEB1 and ZEB2 proteins." (PMID 34923813, 2022). "Cancer cells in CIPCOs showed increased expression of ZEB-1, fibronectin, and vimentin compared with the levels in PCOs." (PMID 35565206, 2022). "Activation of ZEB1 can lead to chemoresistance in different types of cancers via the downregulation of E-cadherin." (PMID 36402997, 2022). "The areas of research covered in this review are contributing to new treatment strategies for cancer by improving our mechanistic understanding of ZEB1-mediated EMT." (PMID 35454770, 2022). "The transcription factor ZEB1 is pivotal in cancer aggressiveness, inducing a stem-like phenotype in cancer cells and invasive behaviour, and although the gene plays a support role in tumorigenesis, its expression was not reported to be carcinogenic per se." (PMID 35205253, 2022). "Mitochondrial ultrastructure analysis by TEM also demonstrated that the ZEB1 silencing led to their morphological elongation in cancer cells." (PMID 35963855, 2022).
cancer (continued). "At the molecular level, Biochanin A decreases the protein stability of ZEB1 via the proteasomal ubiquitination degradation pathway, which is consistent with the notion that ectopic ZEB1 confers chemoresistance in human cancers." (PMID 36512117, 2022). "OGN can reverse EMT by suppressing the EGFR/AKT/Zeb-1 axis, which is an indicator of increased survival and decreased cancer recurrence in colorectal cancer." (PMID 36421687, 2022). "CircFAT1(e2) can sponge miR-873, promoting ZEB1 expression, which modulates cancer progression, invasion, and metastasis." (PMID 36230649, 2022). "Several transcription factors, including Snail1, Slug, and ZEB-1, are involved in the repression of E-cadherin in cancer cells." (PMID 35347116, 2022). "Conversely, the mesenchymal markers fibronectin, N‐cadherin and vimentin, the EMT‐TFs Snail, Slug, Zeb1 and Zeb2, and the cancer stem cell markers CD44, Sox2 and Id1 were strongly induced by TGFβ and repressed by BMP in 3D cultures." (PMID 35348275, 2022). "pERK plays critical roles in cell cycle progression via c-MYC stabilization, EMT via ZEB1 induction, apoptosis, autocrine cytokine loops, cancer metabolism, and protein translation." (PMID 35659728, 2022). "Taken together, our study provides evidence to support a role of lncRNA SNHG6-miR101 axis in tamoxifen resistance of ER-positive breast cancers which involves modulation of EMT and cancer stem cells phenotype through targeting of ZEB1/EZH2." (PMID 36212408, 2022). "EMT transcription factors such as ZEB1/2, SNAIL, and SLUG are associated with the Notch signaling pathway in various cancer cells." (PMID 35455021, 2022). "In The Cancer Genome Atlas, ZEB1 mRNA levels are positively correlated with ITGA1 mRNA levels in multiple cancer types." (PMID 34874914, 2022). "As an example, ZEB1, a major regulator of cancer-cell plasticity, has been identified as an ATM substrate." (PMID 35110528, 2022). "Knockdown of ZEB1 and Snail expression via small interfering RNAs (siRNAs) can improve the sensitivity of cancer cells to chemotherapy." (PMID 35204785, 2022). "We experimentally characterized Nrf2 and the EMT related markers, E-cadherin and ZEB1, during collective migration of cancer cells with immunocytochemistry, fluorescence in situ hybridization (FISH), and a double-stranded single cell biosensor." (PMID 35480877, 2022). "Zeb1 is a typical transcription factor that is widely expressed in carcinomas and has a significant role in the development of cancer by promoting EMT and chemoresistance in cancer cells." (PMID 36071472, 2022). "Previous reports have shown that non-cancer stem cells can be transformed into cancer stem cells when the transcription of Zeb1 increases." (PMID 35611144, 2022). "During the late 2000s, five research groups independently validated that miR-200s strongly repress EMT in multiple cancer types by directly targeting the major EMT transcription factors ZEB1 and ZEB2." (PMID 35740906, 2022). "Zeb1 endows cancer cells with pro-invasive and stem-like phenotypes and determines a relatively poor clinical prognosis in human cancer patients." (PMID 35246504, 2022). "Upregulation of miR-448 expression inhibits cancer cell proliferation and invasion, promotes apoptosis by targeting ZEB1, and increases the sensitivity of the cells to PTX or 5-FU." (PMID 35905576, 2022). "In this study we focused on Set7/9 effect on Zeb1 expression and the role of Set7/9 in regulation of migration potential of cancer cells." (PMID 36517518, 2022). "ZEB1 appears to play a key role in the development of UM cancer stem cell properties and vasculogenic mimicry." (PMID 35404029, 2022). "When ZEB1/2 were upregulated and maintained at high levels in aggressive cancer cells, the IIIc isoforms of FGFRs were expressed through isoform switching when ESRP1/2 expression was repressed." (PMID 36140527, 2022). "Next, we investigated the effects of Biochanin A/ZEB1 on cancer cell metastasis in a xenograft metastasis model." (PMID 36512117, 2022).
cancer (continued). "Concisely, the mRNA and protein expression level of FASN and FADS2 was upregulated in ZEB1 overexpression cancer cells, while downregulated in the ZEB1-S555A mutant cells." (PMID 35844792, 2022). "Understanding the mechanism and functional consequences of ZEB1/YAP-triggered phenotypic plasticity is therefore critical to improve cancer therapeutics." (PMID 35477522, 2022). "Taken together with our present study, these findings shed new light on the mechanisms of Zeb1 in cancer metabolism regulation." (PMID 35246504, 2022). "In analogy with their function, ZEB1 lose the epithelial phenotype and gain the mesenchymal phenotype with motile and migratory abilities in cancer." (PMID 36499447, 2022). "To validate our in vitro observation that ZEB1 O-GlcNAcylation promoted cancer cell ferroptosis sensitivity, we firstly cultured PANC02 cells with or without Thiamet-G and then injected subcutaneously into C57BL/6J mice." (PMID 35844792, 2022). "Exosomes derived from hepatocellular carcinoma cells can induce ERK signaling to mediate EMT via upregulation of ZEB1/2, leading to cancer metastasis." (PMID 35765040, 2022). "Inhibition of FTO with shRNAs was sufficient to suppress the expression of ZEB1 and Vimentin, promote E-cadherin expression levels, and attenuate docetaxel resistance of cancer cells following SN-exo incubation." (PMID 36302751, 2022). "Several recent studies have identified the posttranslational modifications for the regulation of ZEB1 protein levels in cancer development." (PMID 36512117, 2022). "Numerous papers have reported that gene silencing of ZEB1, as well as Snail, inhibits migration and invasion of various kinds of cancer cells." (PMID 35451213, 2022). "Meanwhile, high positive rate of CSN5, GATA1 and ZEB1 in cancer tissues detected by immunohistochemistry and we showed that expression of SENP1 is positively correlated with expression of CSN5, GATA1, ZEB1 in our TNBC samples." (PMID 35342335, 2022). "The aberrant expression of ZEB1 has been reported in a variety of human cancers, where it is generally believed to foster migration, invasion, and metastasis via mTOR signaling." (PMID 36077992, 2022). "The ZEB1 transcription factor is a primary regulator of EMT; high ZEB1 expression levels have been shown to contribute to development of several cancers and serve as an apparent predictor of poor overall survival of cancer patients." (PMID 35963855, 2022). "EMT-related transcription factors such as ZEB1, snail, and twist are the important links that regulate the expression of epithelial genes and thus affect the invasion and metastasis of cancer cells." (PMID 36613521, 2022). "Analysis of data from The Cancer Genome Atlas further supported these findings by showing that high ZEB1 expression in tumors corresponded with low levels of CIN." (PMID 35027548, 2022). "Mesenchymal phenotype of cancer cell is tightly regulated by the key transcription factors, such as ZEB1, Snail, and Slug." (PMID 35844792, 2022). "For example, the miR-200 family members miR-200a, miR-200b, miR-429 and miR-141, which are known to act as TSs in many cancers, are reported to target PD-L1 expression and Zinc Finger E-Box Binding Homeobox 1 (ZEB1) in NSCLC." (PMID 36189271, 2022). "In line with this, various functional studies showed that the down-regulation of miR-200 induced EMT, whereas its overexpression provoked mesenchymal-to-epithelial transition (MET) and inhibited cancer cell motility by repression of ZEB1 and ZEB2." (PMID 36011331, 2022). "The silencing of the E-cadherin encoding gene, CDH1, is mediated by the EMT-promoting transcription factors ZEB1 and Snail, two regulators that are overexpressed in many cancers, and which act jointly to repress both CDH1 and LARGE2 mRNAs." (PMID 36494657, 2022). "Zeb1 promotes cancer progression through a combination of genetic, epigenetic, and transcriptional mechanisms." (PMID 35246504, 2022).
cancer (continued). "In MLL-AF9 driven acute myeloid leukaemia (AML), poor prognosis in patients correlated with expression of EMT markers and experimental downregulation of ZEB1 in AML cells inhibited the invasive capacity of this aggressive cancer." (PMID 35203300, 2022). "We next downregulated circ-ZEB1, suggesting the upregulated miR-199a-3p levels and verifying that miR-199a-3p blocked the cancer-promoting effect of circ-ZEB1." (PMID 35277182, 2022). "ZEB1 is a miR-5590-3p downstream target, so its overexpression promotes cancer cell migration and metastasis by inducing the PD-1/PD-L1 axis." (PMID 36612180, 2022). "The EMT program is tightly regulated by key inducers, including the E-box binding motif transcription factor Zeb1, which has been reported to confer stem-cell-like characteristics in cancers." (PMID 36008379, 2022). "Treatment with ATRA significantly downregulated ZEB-1, fibronectin, and vimentin in cancer cells in CIPCOs." (PMID 35565206, 2022). "Globally, staining was noted in stromal cells but not in epithelial malignant cells (only one patient with high transcriptomic ZEB1 expression showed weak ZEB1 expression in cancer cells)." (PMID 36119118, 2022). "ZEB1, as a transcription factor, can participate in cancer progression, especially in EMT progression." (PMID 36273188, 2022). "Previous research works showed that ZEB1 can improve immune evasion by upregulating the expression of PD-L1 in cancer cells." (PMID 35464451, 2022). "Our study thus revealed a possible mechanism of M2-like TAM infiltration into the hypoxic TME via Zeb1-driven aerobic glycolysis in cancer cells." (PMID 35246504, 2022). "When Ets1/2 were knocked down in these cells, expression of Snail, as well as ZEB1/2, were suppressed, suggesting that Ets1/2 maintains expression of not only Snail but also ZEB1/2 in cancer cells." (PMID 35451213, 2022). "NETs enhance the expression of EMT markers ZEB1, Snail and fibronectin, cancer stem cell marker CD44, proinflammatory mediators, such as IL1β, IL6, IL8, CXCR1, MMP2 and MMP9." (PMID 35574410, 2022). "Zinc finger E-box binding homeobox 1 (ZEB1) is a pleiotropic transcription factor frequently expressed in carcinomas." (PMID 35454770, 2022). "The expression of Zeb1 decreased over time of mouse ESCs differentiation but significantly increased in mouse embryonal carcinoma cells." (PMID 35611144, 2022). "This study was adopted to understand the roles and possible mechanisms of LINC-PINT in cancer development with regard to the regulation of ZEB1 expression." (PMID 34257531, 2021). "The upregulation of ZEB1 expression was revealed to partly reverse the suppressive effects of LINC-PINT overexpression on cancer cell proliferation, invasion and migration abilities." (PMID 34257531, 2021). "The EMT-associated transcription factors Zeb1, Snail1, and Twist1 play roles in the regulation of EMT during the metastasis of cancer cells through different signaling cascades, including the Akt and ERK1/2 pathways." (PMID 33567682, 2021). "Mechanistically, high ZEB1 levels in mesenchymal cancer cells were responsible for transcriptional repression of p21 by direct binding to the promoter region." (PMID 34309585, 2021). "Numerous studies have reported that ZEB1 contributes to cancer progression, while the role of CRYAB and SQLE in BC is rarely reported." (PMID 34490263, 2021). "Knockdown of ZEB1 restores drug sensitivity and increases the expression of epithelial markers in cancer cells showing mesenchymal characteristics." (PMID 33768509, 2021). "The Crk mechanism for enhancing cancer metastasis was achieved by upregulating the expression of Zeb1 and N-cadherin and repressing E-cadherin levels." (PMID 34069461, 2021). "Recent research reports that an EMT program needs to be transient and reversible and that a mesenchymal phenotype in cancer cells is achieved by constitutive ectopic expression of ZEB1." (PMID 34919051, 2021).